MSH3 (mutS homolog 3)
Diseases named in the same sentence as MSH3 in open-access papers (continued):
Sharing a sentence is not in itself a finding about the gene and the disease.
Huntington disease (22 papers, 2011 to 2026). Huntington disease (HD) is a rare neurodegenerative disorder of the central nervous system characterized by unwanted choreatic movements, behavioral and psychiatric disturbances and dementia. "Available data indicate that successful MSH3-targeting treatments will slow down the rate of somatic CAG repeat expansion in the brains of Huntington's disease mutation carriers." (PMID 38387080, 2024). "We next examined the relationship between cognitive function and five genetic polymorphisms linked to genes known to affect cognitive function in Huntington’s disease: MSH3, FAN1, MAPT, BDNF and COMT." (PMID 36519153, 2022). "In summary, our study provides additional evidence for the beneficial role of intellectual enrichment and carrying the 3a allele in MSH3 in cognitive function in Huntington’s disease and their effect on brain structure." (PMID 36519153, 2022). "Remarkably, one of the loci in MSH3 modifying AAO in XDP has been associated, also by GWAS, with disease progression in Huntington’s disease (HD), and signals in MSH3, PMS2, and other DNA maintenance genes modify AAO in HD and DM." (PMID 38835911, 2022). "Collectively, our results suggest the MSH3 3a repeat allele reduces somatic expansion and improves phenotype in both Huntington’s disease and DM1, potentially through altering MSH3 expression levels." (PMID 31216018, 2019). "The mismatch repair gene MSH3 has been implicated as a genetic modifier of the CAG·CTG repeat expansion disorders Huntington’s disease and myotonic dystrophy type 1." (PMID 31216018, 2019). "A transcriptome-wide association study in the Huntington’s disease cohort found increased MSH3 and DHFR expression are associated with disease progression." (PMID 31216018, 2019). "RNA-Seq of whole blood in the Huntington’s disease subjects found that repeat variants are associated with MSH3 and DHFR expression." (PMID 31216018, 2019). "LIG1 and RRM2B were both associated with neurofibrillary tangles, which may provide a link to a potential role in mHTT aggregates, while MSH3 was associated with several cortical morphology-related traits relevant to Huntington’s disease." (PMID 39801710, 2025). "A recent Huntington’s disease genome-wide association study found rs557874766, an imputed single nucleotide polymorphism located within a polymorphic 9 bp tandem repeat in MSH3/DHFR, as the variant most significantly associated with progression in Huntington’s disease." (PMID 31216018, 2019). "Re-analysis of Huntington’s disease AOO exome sequencing data showed that, in the early onset Huntington’s disease group, deleterious variants were enriched in FAN1 and depleted in LIG1, MSH3 and PMS1." (PMID 39801710, 2025). "Cortical thinning is observed in Huntington’s disease, even during the prodromal phases before disease onset, so understanding how MSH3 contributes to cortical morphology in general and brain atrophy is important." (PMID 39801710, 2025). "Western blot showed that the HTT1a smear was visually reduced in most of the Q111 Huntington’s disease mice treated with MSH3-1000 compared to NTC." (PMID 40926977, 2025). "Potential treatments targeting MSH3 currently under development include gene therapy, biologics and small molecules, which will be assessed for efficacy in mouse models of Huntington's disease." (PMID 38387080, 2024). "The strongest candidate gene in this locus is Msh3, a known modifier of STR stability in cancer and at pathogenic repeat expansions in mice and humans, as well as a current drug target against Huntington's disease." (PMID 37127331, 2023). "Khvorova and colleagues demonstrate that the delivery of a di-valent siRNA to the CNS silences MSH3 and blocks disease-associated somatic expansion of CAG repeats in two Huntington’s disease mouse models." (PMID 37177784, 2023).
Huntington disease (continued). "In terms of genetic polymorphisms, we selected common polymorphisms that have been previously associated with cognitive function in Huntington’s disease [COMT, brain-derived neurotrophic factor (BDNF), FAN1, MSH3 and MAPT]." (PMID 36519153, 2022). "These regions harbor or lie adjacent to MSH3 and PMS2, the genes that were recently implicated in modifying age at onset in Huntington’s disease, likely through a common pathway influencing repeat instability." (PMID 34050153, 2021). "Msh3, as well as Mlh1, were also shown to be specifically involved in expansions in a transgenic mice model for Huntington’s disease." (PMID 33925919, 2021). "This preliminary study elucidates variation in MSH3 that modifies Huntington’s disease and identifies the same signal in an independent trinucleotide repeat disease." (PMID 31216018, 2019). "Whole blood transcriptomic analysis in a subset of the Huntington’s disease patients found the 3a allele was associated with reduced expression of MSH3 and DHFR, and seven- or eight-repeat alleles with increased MSH3 expression." (PMID 31216018, 2019). "Rs1677658 was associated with reduced MSH3 and DHFR expression (CMC and GTEx), whereas rs1650697 was associated with increased DHFR in Huntington’s disease blood, as well as multiple tissues in GTEx." (PMID 31216018, 2019). "Our TWAS found that increased expression of MSH3 and DHFR in cortex are associated with faster Huntington’s disease progression." (PMID 31216018, 2019). "We conducted targeted Illumina sequencing of the MSH3 exon 1 region in 218 Huntington’s disease and 247 DM1 subjects, which allowed us to obtain accurate haplotype information for the region." (PMID 31216018, 2019). "The MSH3 signal in the GWAS of Huntington’s disease progression was driven by an imputed SNP, rs557874766, located within a 9 bp tandem repeat sequence in exon 1 of MSH3, which is also in the 5′ UTR of DHFR on the opposite strand." (PMID 31216018, 2019). "When removing count-based terms, we visualized 11 signals from four Huntington’s disease modifier genes (MSH3 n = 8, LIG1 n = 1, MLH1 n = 1, RRM2B n = 1), some of which are related to neurological processes that could be relevant to Huntington’s disease." (PMID 39801710, 2025). "Interestingly, Msh3 was also shown to be driving expansions in a mouse model for Huntington’s disease." (PMID 33925919, 2021). "Additionally, MSH3 has an effect on the phenotype of Friedreich’s ataxia and Huntington’s disease, both trinucleotide repeat disorders." (PMID 32157568, 2020). "This favours MSH3 over DHFR expression as a modifier of Huntington’s disease course." (PMID 31216018, 2019). "Using whole blood RNA-Seq in Huntington’s disease, we investigated whether sequence variation at the MSH3/DHFR locus influences their expression." (PMID 31216018, 2019). "DHFR, which shares a promoter with MSH3, is a ubiquitously expressed enzyme involved in purine, thymidylic acid and amino acid synthesis, but has not previously been implicated in Huntington’s disease pathogenesis." (PMID 31216018, 2019). "A total of five Huntington’s disease modifier genes (FAN1, MLH1, MSH3, PMS2 and RRM2B) had OMIM phenotype entries, mainly for cancer-related diseases for DNA-repair-related genes." (PMID 39801710, 2025). "MSH3 has recently been identified as a genetic modifier of somatic instability in DM1, and progression in Huntington’s disease." (PMID 31216018, 2019). "For this purpose, we analysed data from Track-HD, a multi-centre longitudinal study in Huntington’s disease gene carriers and focused on the role of intellectual enrichment (estimated at baseline) and the genes FAN1, MSH3, BDNF, COMT and MAPT in predicting cognitive decline and brain atrophy." (PMID 36519153, 2022).
Huntington disease (continued). "This is consistent with Huntington’s disease mouse brain, in which expression of MSH3, but not DHFR, correlates with somatic expansion." (PMID 31216018, 2019). "The trajectory for repeat expansion in the Huntington's disease brain is not understood and these results indicate that the greatest benefit for MSH3-targeting therapeutics will be realized by treating as early as possible before cell-specific pathogenic thresholds have been achieved." (PMID 38387080, 2024).
Lynch syndrome (20 papers, 2008 to 2024). "Recent studies have associated mutS homolog 3 (Msh3) variants, which play key roles in mismatch repair alongside other genes, with Lynch syndrome." (PMID 32168507, 2020). "Germline mutation of MSH6, a component of MutSα, causes a more moderate Lynch syndrome phenotype presumably due to overlap with MSH3 (MutSβ function) coupled with a compensatory increase in MSH3 expression." (PMID 25836926, 2015). "Of these, five mutations (9.26%, 5/54) were in homologous recombination repair (HRR) pathway genes, including PALB2 (1.85%, 1/54), BLM (1.85%, 1/54), NBN (1.85%, 1/54), RAD51C (1.85%, 1/54), and RAD51D (1.85%, 1/54), and one mutation was in MSH3 (1.85%, 1/54) related to Lynch syndrome." (PMID 33194720, 2020). "Recent studies have shown that virtually all (99%) CRCs developing in Lynch syndrome patients display MSI-H; the most mutated genes exhibiting microsatellite repeats are ACVR2A, TGFBR2, EGFR, BPMR2, E2F4, MSH3, BAX and TCF7L2." (PMID 29652830, 2018). "On the other hand, germline defects in both MutSalpha proteins, but not MSH3, are implicated in Lynch syndrome, a common cause of hereditary colon cancers characterized by high rates of MSI." (PMID 37127331, 2023). "Similarly to Lynch syndrome, the adenoma-carcinoma sequence may be accelerated in MSH3-related adenomas." (PMID 35675019, 2023). "In the MSI pathway observed in Lynch syndrome, CRC formation is driven by the acquisition of mutations at the level of the coding sequences of genes, such as growth factor receptors (TGFBR2 and IGF2R), genes involved in apoptosis (BAX) and DNA repair (MSH3 and MSH6)." (PMID 29652830, 2018). "There has been no description of a germline MSH3 mutation as a cause of Lynch syndrome." (PMID 25836926, 2015). "The results may partially explain why Msh3-knockout mice exhibit normal life-span and only late onset of tumor development, or why germline mutations of MSH3 are not detected in families with Lynch syndrome." (PMID 23209772, 2012). "MSH3 also directly and indirectly interacts with breast cancer susceptibility gene product (BRCA1) and BRCA1-associated RING domain protein 1 (BARD1) which may partially provide an explanation for the background of gynecological and CRC in both Lynch syndrome and BRCA1 individuals." (PMID 23209772, 2012). "Inactivating mutations of MSH3 is considered a low-risk allele that contributes to development of hereditary nonpolyposis colorectal cancer (HNPCC), or Lynch syndrome." (PMID 32393201, 2020).
colon carcinoma (16 papers, 2010 to 2026). "In summary, MSH3 deficiency confers increased sensitivity to oxaliplatin and SN-38, but not 5-FU, in association with increased DNA DSBs in isogenic colon cancer cell lines." (PMID 23724141, 2013). "In MLH1-deficient human colon cancers, loss of MSH3 protein expression was found in 37–48% of tumors." (PMID 23724141, 2013). "TGFBR2 and MSH3 mutations were detected more frequently in right MSI-H colon carcinomas (P = 0.00005 and P = 0.0000005, respectively) than in MSI-H rectal and sigmoid carcinomas." (PMID 20979647, 2010). "Similarly, Berndt and al reported that processed meat intake modified risk of colon cancer from two common variants in another MSH3 gene of MMR system." (PMID 28451866, 2018). "Takahashi and colleagues have also suggested that human colon cancer cell lines that have diminished expression of MSH3 are sensitive to platinum-based treatment." (PMID 39003369, 2024). "In our study, MSH3 gene had significantly higher expression levels in colon tumors when compared to adjacent mucosa." (PMID 24484585, 2014). "Specifically, significantly higher expression levels of MSH3 gene were observed in colon tumors when compared to adjacent mucosal tissue (1.18 fold change, P = 0.02)." (PMID 24484585, 2014). "We have found significantly increased transcription levels in EXO1 gene in tumor tissues (P = 0.05) and significant over-expression of MSH3 gene in colon tumors when compared to adjacent mucosal tissues (P = 0.02)." (PMID 24484585, 2014). "First, we examined mutational specificity in the HCT116 human colon cancer cell line, which carries loss-of-function mutations in both the MLH1 and MSH3 genes and has been previously shown to be deficient in repair of two-nucleotide loops." (PMID 23450065, 2013). "Using isogenic colon cancer cell lines in which MSH3 expression was suppressed by a Tet-on system or by constitutive knockdown, we found that the cytotoxic effects of SN-38 and oxaliplatin were dependent upon MSH3 status." (PMID 23724141, 2013). "In support of our data in isogenic HCT116 cells, we also generated SW480 colon cancer cells with suppression of MSH3." (PMID 23724141, 2013). "So far, two studies have reported that in MTX-resistant cell lines, the promyelocytic leukemia HL-60 cell line and the colon cancer cell line HT-29, DHFR and MSH3 were often co-amplified, leading to an overexpression of both genes." (PMID 38074116, 2023).
breast carcinoma (15 papers, 1999 to 2025). "A breast cancer and a prostate cancer developed by MSH3 heterozygotes had MSH3 LOH causing the loss of the wildtype allele." (PMID 40237887, 2025). "There are reports in the literature on other Msh3 polymorphisms involved in radiosensitivity of breast cancer patients." (PMID 25079915, 2014). "We carried out a hospital-based case-control study in a Caucasian Portuguese population (287 cases and 547 controls) to estimate the susceptibility to non-familial breast cancer associated with some polymorphisms in mismatch repair genes (MSH3, MSH4, MSH6, MLH1, MLH3, PMS1 and MUTYH)." (PMID 19781088, 2009). "For some genes, single P/LP variants were detected either only in the group of patients with breast cancer (APC, MDM1, MRE11, POLD1, NF1, RAD51C, RECQL4, and WRN) or only in the control group (MCPH1, MSH3, and XPC)." (PMID 39684352, 2024).
polyposis (9 papers, 2021 to 2026). "Pathogenic biallelic germline variants in MSH3 are also associated with colorectal polyposis, namely, MSH3-associated polyposis." (PMID 38647838, 2024). "The incidence of MSH3-associated polyposis appears to be extremely rare, and only three families reported to date." (PMID 38243056, 2024). "The most recently identified polyposis syndromes are NTHL1-associated polyposis and MSH3-associated polyposis." (PMID 33922305, 2021). "The age of onset and severity of polyposis may, next to the biallelic MSH3 variants, be influenced by differences in other genetic and/or environmental factors." (PMID 35675019, 2023). "Three patients from two families with MSH3-associated polyposis were included." (PMID 34843512, 2021). "Two siblings with a known history of adenomatous polyposis (subjects II.2 and II.5) carried the same compound heterozygous MSH3 variants, as well as one other sibling (II.11) without a known polyposis." (PMID 35675019, 2023). "To date, only two families with MSH3-related polyposis have been described." (PMID 34843512, 2021). "It is not known whether this is due to the specific nature of the MSH3 variants or if some additional factor is necessary for the onset of polyposis." (PMID 38243056, 2024). "Unfortunately, no malignant tissue was available from the few MSH3-related polyposis patients." (PMID 34843512, 2021).